IL4 (interleukin 4)
Diseases named in the same sentence as IL4 in open-access papers (continued):
Sharing a sentence is not in itself a finding about the gene and the disease.
schistosomiasis (continued). "Schistosomiasis diagnosis was confirmed through urine microscopy using filtration methods, while full blood count and cytokine (IL-4, IL-10) analysis were performed on blood samples." (PMID 40526709, 2025). "According to studies, parasite antigens are sensitized in neonates of women who have helminth illnesses such schistosomiasis and filariasis, which are characterized by the production of IL‐4, IL‐5, IgE, and IFN‐ γ." (PMID 39560407, 2024). "The production of IL-4 and IL-13 from basophils downregulates inflammatory responses in schistosomiasis as these cytokines result in the differentiation of monocytes to alternatively activated macrophages." (PMID 39481080, 2024). "Schistosomiasis is characterized by a robust Th2 (T-helper 2) immune response, marked by the production of cytokines such as IL-4, IL-5, and IL-13." (PMID 39452777, 2024). "The cytokine IL-4 is important to initiate the type Th2 response, which is important in schistosomiasis physiopathology, and is well established to be essential for altering the IgE antibody type." (PMID 37111413, 2023). "Cytokines such as TNF-α, IL-1β, IL-6, IL-4, and IL-10, among others, show increased serum levels during schistosomiasis, reflecting the polarization and complexity between Th1 and Th2 immune responses." (PMID 38239348, 2023). "IL-4 is recognized as the dominant cytokine for Th2 response and granuloma development, as the Th1 response during the early stages of schistosomiasis is downregulated by IL-4 and -10." (PMID 37276235, 2023). "During schistosomiasis, Th2-derived IL-4/IL-13 contributes to the activation of macrophage-derived TGF-β, leading to severe pulmonary vascular remodeling." (PMID 37908354, 2023). "Blocking PGE2 receptors (EP2 and EP4) in the early schistosomiasis would limit IL-4 and IL-10 production." (PMID 35396684, 2022). "Genetic studies have revealed associations between SNPs in genes encoding cytokines and TFs and susceptibility to schistosomiasis, including in STAT6, IL4, IL5, IL10, and IL13." (PMID 35759449, 2022). "In clinical studies, Tfh cells were associated with immune responses to both acute and chronic human schistosomiasis and IL-4 producing Tfh cells are thought to provide acquired resistance to schistosome re-infection." (PMID 35592327, 2022). "Studies have indicated that newborns of mothers infected with helminth infections such as schistosomiasis and filariasis are sensitized with parasitic antigens with a predominant Th2 environment characterized by production of IL-4, IL-5, IgE and IFN-γ." (PMID 35592327, 2022). "The genes with the largest literature were the Th2 cytokine genes originally identified by Marquet in SM1 (IL3, IL4, IL5, IL9, and IL13), that each had between 17 and 511 publications associated with schistosomiasis." (PMID 33659002, 2021). "IL13 and IL4 regulate STAT6 expression which in turn regulates IgE class switching and STAT6 variants are also associated with schistosomiasis." (PMID 33659002, 2021). "We have established a novel experimental murine model of maternal schistosomiasis in IL-4 dual reporter mice." (PMID 33524040, 2021). "Here, we investigated the effects of maternal Schistosoma mansoni infection on steady-state offspring immunity, as well as immunity induced by a commercial tetanus/diphtheria vaccine using a dual IL-4 reporter mouse model of maternal schistosomiasis." (PMID 33524040, 2021). "This was shown in mice immunized with schistosome egg antigens (SEA) and complete Freunds adjuvant, and again in mice that lack both IL-10 and IL-4, which reached 100% mortality upon infection with schistosomiasis." (PMID 33304354, 2020). "Monocytes and macrophages exert important roles during schistosomiasis, while high levels of Th2 cytokines (IL-4 and IL-13) have profound phenotypical and functional impact on these cells." (PMID 32922381, 2020).
schistosomiasis (continued). "IL-4, also evaluated in the present study, is an immunological mediator, plays an important role in pathogenesis of schistosomiasis, with participation in fibrosis and granulomas formation." (PMID 31015492, 2019). "The cytokine levels of TNF-α, IFN-γ, IL-6, IL-4, IL-5, IL-10, IL-13, and IL-17A in the sera of acute phase schistosomiasis were all significantly increased in the IUT and VEH groups compared with the UI group." (PMID 30258438, 2018). "As a major source of IL-4 in helminth infections, including schistosomiasis, basophils have been identified." (PMID 30364177, 2018). "Previously, we found that IPSE/alpha-1 triggers the release of IL-4 and IL-13 from human and murine basophils, suggesting that this molecule is involved in inflammation control in schistosomiasis." (PMID 30364177, 2018). "Using inducible IL-4Rα deficient mice in the present study, we now dissected the role of IL-4/IL-13-mediated type 2 responses during acute and chronic murine schistosomiasis." (PMID 28827803, 2017). "Specific cytokines, in particular IL-2, IL-4, IL-5, IL-10, and IFN-ɤ have been implicated in regulation of granulomatous response on schistosomiasis." (PMID 27378927, 2016). "The pathology characterized by granuloma formation around the eggs in the murine model of schistosomiasis is related to Th2 cytokines, such as IL-4 and IL-13." (PMID 25942636, 2015). "Remarkably, for intestinal goblet cell hyperplasia in schistosomiasis signalling by IL-4/IL-13 is dispensible." (PMID 25398130, 2014). "An increase in Th2 responsiveness does occur with treatment of schistosomiasis with greater IL-4 and IL-13 in vitro responses to SWA being measured 7-wk, and beyond, post-treatment." (PMID 23556029, 2013). "Pathology resulting from granuloma formation around the eggs in murine schistosomiasis is characterized by Th2-type of immune response and the granuloma size can be reduced by neutralization of IL-4." (PMID 23209848, 2012). "Studies in schistosomiasis demonstrated that the development of fibrosis requires the production of the profibrotic cytokines IL-4 and IL-13." (PMID 21629648, 2011). "For example, both Th1 and Th2 responsiveness appear compromised in schistosomiasis patients, and within the Th2 compartment, IL-5 responses are suppressed while IL-4 production is relatively intact." (PMID 21039611, 2010). "Field studies in schistosomiasis and filariasis as well as mechanistic experimental studies have reported dissociation in IL-4 and IL-5 production and effector functions." (PMID 21039611, 2010). "Because production of the soluble IL-13Rα2 is IL-4Rα-, IL-13Rα1-, and Stat6-dependent, these data combined with the schistosomiasis studies suggested that the Retnla−/− mice were developing stronger IL-4/IL-13 responses following infection." (PMID 19381262, 2009). "Pathology which results from granuloma formation around the eggs in murine schistosomiasis is characterized by Th2-type of immune response and the granuloma size can be reduced by neutralization of IL-4." (PMID 18827884, 2008). "IL-4 and IL-10 have well-established and complementary roles in schistosomiasis immunobiology." (PMID 40526709, 2025). "In the adjusted multivariate model, IL-4 (AOR: 1.007, 95% CI: 1.003–1.012, p = 0.0011) and lymphocyte count (AOR: 2.956, 95% CI: 1.186–7.364, p = 0.0199) remained independently associated with schistosomiasis." (PMID 40526709, 2025). "While the typical T helper 2 (TH2)-skewed immune response to schistosomiasis is well-documented, the age-specific dynamics of key immunological markers, principally involving IL-4 and lymphocyte profiles, remain poorly characterized in endemic Zambian populations." (PMID 40526709, 2025). "Although egg production is the main driver of type 2 immune responses in schistosomiasis, some studies have shown that antigen-specific type 2 responses, characterized by IL-4 production, can already be detected in prepatent infections (4 weeks) or in single-sex S. mansoni infections." (PMID 39563428, 2024).
schistosomiasis (continued). "Noteworthy, since LTC4 is known to function also as an intracrine signal capable of triggering IL-4 secretion from eosinophils, cysLTs may emerge as immunoregulators of the IL-4-mediated type 2 immune response of schistosomiasis." (PMID 39173086, 2024). "Large amounts of IL-4 are produced in S. mansoni-infected mice and are proposed to be responsible for granuloma formation, and cytokine IL-10 is fundamental for generating host-protective homeostatic circumstances in schistosomiasis." (PMID 36362992, 2022). "In addition, we identify novel dominant protective and risk alleles at IL4 rs2070874*T and IFNG rs2069727*G, respectively, for urogenital schistosomiasis and significantly associate the IFNG gene with schistosomiasis susceptibility for the first time." (PMID 35759449, 2022). "The Th1 response during the early stage of schistosomiasis is downregulated by IL-4 and IL-10." (PMID 32132991, 2020). "Additionally, it is well described that IL-4/IL-13-activated alternative macrophages are essential for surviving acute schistosomiasis." (PMID 23209848, 2012). "The most interesting findings are on the differential expression of IL-4 between pediatric and adult populations, along with the consistent involvement of lymphocytes across all age groups, suggesting distinct but overlapping immune mechanisms in the host response to schistosomiasis." (PMID 40526709, 2025). "To test whether IL-4/IL-13-induced arginase activity in macrophages was critical to the development of morbidity and mortality in schistosomiasis, we analyzed the survival of Arg1flox/flox and Arg1−/flox;LysMcre mice following infection with S. mansoni cercariae." (PMID 19360123, 2009). "This shift from a Th1- to Th2-skewed response significantly contributes to liver fibrosis in schistosomiasis, characterized by a decrease in IFN-γ (Th1 cytokine) and an increase in IL-4, IL-5, and IL-13 (Th2 cytokines) profiles." (PMID 39481080, 2024). "Cytokines, such as IL-4, IL-10, IFN-γ, IL-17, and IL-9, have been reported to be key signals in the immune cells involved in schistosomiasis." (PMID 33628844, 2021). "Our data from this model demonstrate that maternal schistosomiasis reduces steady-state iNKT and CD4-T cell production of IL-4." (PMID 33524040, 2021). "IL-4 decreases the production of Th1 cells, macrophages, IFN-gamma, and dendritic cell and IL-12189; thus, plays a protective role during schistosomiasis by controlling the production of other cytokines." (PMID 31024947, 2019). "We previously reported that patients with schistosomiasis and HIV coinfection had significantly lower production of the cytokines IL-4 and IL-10 than schistosome-infected persons who were HIV negative." (PMID 20351784, 2010). "This indicates that whilst IL-4 inhibits megakaryopoiesis, this either does not occur in schistosomiasis or the impact of infection-induced IL-4 is only transient." (PMID 41296814, 2025). "While IL-4 showed no independent association in pediatric participants (AOR 1.001, p = 0.0715), it emerged as a strong associate of schistosomiasis in adults (AOR 1.007, p = 0.0011)." (PMID 40526709, 2025). "During murine schistosomiasis, NKT cells could recognize glycolipids presented by CD1d on APCs, inducing the production of type 2 cytokines (IL-4, IL-5, IL-13) and influence the Th1/Th2 balance of the immune response." (PMID 36618421, 2022). "IL13, IL4, IL5, and STAT6 are also involved in regulation of the Th2 response to schistosomiasis." (PMID 33659002, 2021). "Others have demonstrated that NFAT−/− mice have increased eosinophil and serum levels of IgE and that NFAT family proteins positively regulate IL-4 production, suggesting that NFAT may play a role in the Th2 response in schistosomiasis." (PMID 32636844, 2020). "Overall, it is known that IL-4 and IL-13 play redundant roles in the schistosomiasis granulomatous response, but IL-13 is not dependent on profibrotic cytokines or affected by Th1/Th2 cytokines." (PMID 32132991, 2020).
schistosomiasis (continued). "However, during the chronic phase of schistosomiasis, the levels of TNF-α, IFN-γ, IL-6, IL-4, IL-10, and IL-17A remained increased in the IUT and VEH groups." (PMID 30258438, 2018). "We show that in response to IL-4 and IL-13, Lyz2loIL-4Rα+ macrophages differentiate into an arginase 1-expressing alternatively-activated macrophage (AAM) population, which slows the development of lethal fibrosis in schistosomiasis." (PMID 25211233, 2014). "Despite the well-documented dominance of the Th2 response during schistosomiasis, it is clear that in this infection macrophages do not conform fully to the M2 phenotype observed in IL-4 stimulated bone marrow derived macrophages." (PMID 25144366, 2014). "This reinforces the notion that eosinophil elevation in schistosomiasis may be a downstream consequence of IL-4, driven immune polarization, rather than a primary immune event as previously held." (PMID 40526709, 2025). "Another limitation is the reliance on single measurements of laboratory markers such as IL-4 and eosinophils may not fully capture the dynamic nature of the immune response in schistosomiasis." (PMID 40526709, 2025). "These cellular changes were accompanied by a significant reduction in Th2 cytokines IL-4 and IL-5 in Cre+ MGL2+ CD11b+ cDC2 depleted mice, as a proportion of CD4+ T cells, implicating Irf4-dependent dependent cDC2s as critical in promoting type-2 responses during pre-patent schistosomiasis." (PMID 37012228, 2023). "However, there was no tendency of correlation between the level of IL-4 and the level of HA in mouse schistosomiasis, it possibly only contributes liver granulomatous formation, but not liver fibrogenesis." (PMID 29192177, 2017). "Given the importance of IL-4 and IL-4 signaling for host protection, and knowing that basophils are a source of IL-4, we asked in this study whether IPSE/alpha-1, as a potent inducer of basophil IL-4/IL-13, might be involved in the control of inflammation in schistosomiasis." (PMID 30364177, 2018). "Interestingly, whereas all eGFP+ CD4 T cells during schistosomiasis preserved CD200R, only a proportion secreted IL-4 indicating that not all Th2-primed cells acquired/retained effector function." (PMID 22496920, 2012).
Granuloma (71 papers, 2008 to 2025). A compact, organized collection of mature mononuclear phagocytes, which may be but is not necessarily accompanied by accessory features such as necrosis. "Increased levels of IL-4 and IL-10 can affect Mtb-induced granuloma and are linked to an increased bacterial burden, and more severe TB and LTBI recurrence." (PMID 39514524, 2024). "Considering the effects observed in IL-10/IL-12-deficient mice, the improvement of fibrotic granulomas seemed to be dependent on the fine-tuning of Il4, Il10, and Il12." (PMID 39404406, 2024). "IL-4 and IL-13 determine the inflammatory phenotype of egg-induced granulomas and IL-13 causes fibrosis." (PMID 29743881, 2018). "Consistently, the expression of IL-12 both in serum and within granulomas was increased in S. japonicum-infected SR-A-deficient mice, while IL-4 decreased significantly." (PMID 28695899, 2017). "When we analyzed the lung pathology in the IL-4−/− control group, we observed smaller and more compact granulomas associated with diminished fungal burden when compared with WT control group." (PMID 21731741, 2011). "Moreover, infected KO rats displayed a marked decrease in the levels of both Th1- (IFN-γ) and Th2-associated cytokines (IL-4, IL-5) at all time points post-infection, except with IL-2 and IL-13, both of which play an important role in granuloma and fibrosis development." (PMID 35584107, 2022). "Consistent with the higher RVSP, the size of peri-vascular granulomas was modestly larger, although the concentrations of IL-4 and IL-13 were unchanged in S. mansoni-exposed mice." (PMID 41055564, 2025). "The results demonstrate that immunotherapy with the enzyme HGPRT seems to stimulate the production of IL-4 and promoted a significant reduction of granulomas in the liver in treated animals." (PMID 37111413, 2023). "In that study, IL-4 was shown to play a redundant role in granuloma formation, as evidenced by the ability of IL-4 knockout mice to form perioval granulomas." (PMID 36505463, 2022). "It is well known that interleukin 4 (IL-4) and IL-13-mediated type II immune response leads to the development of granulomas around eggs trapped." (PMID 35930537, 2022). "Cytokines such as IL-1β, IL-4 IL-5, IL-6, IL-13, TNF-α, MCP-1, and TSLP induce allergy-related inflammation, which causes tissue fibrosis, granuloma formation, and leukocyte infiltration." (PMID 36235405, 2022). "The role of individual Th2 cytokines in granuloma formation and fibrosis have been shown to be different in that IL‐4 or IL‐13 can both generate granuloma formation, while IL‐13 alone is the dominant pro‐fibrotic cytokine in this disease." (PMID 32692855, 2021). "Most experimental studies demonstrate the role of Th2 cytokines (IL-4, IL-5, and IL-13) in the formation of granuloma and of the Th17 response in advanced fibrosis." (PMID 34970264, 2021). "Classically, the granuloma evolution is related to a Th2 cytokine profile (i.e., IL-4, IL-5, and IL-13) and lower IFN-γ expression." (PMID 31019973, 2019). "The polarising inflammation toward Th2 response and the Th-1/Th-2 cross-regulation and the growth of granuloma formation is mainly mediated by IL-4 and IL-13." (PMID 31024947, 2019). "Comparison between the pro- and anti-inflammatory cytokines in granulomas revealed that IL-4 expression was significantly higher when compared with IL-6 (p=0.001) and TNF-α (p=0.001)." (PMID 29898177, 2018). "By day 80 PI, incipient granulomas were detected in the hepatic parenchyma and staining for IL-4 was observed in isolated and small clusters of lymphocytes." (PMID 29899533, 2018). "In the present study, with the help of NP30 immunization, the beginning of the deposition of eggs in livers and the formation of granulomas result in the differentiation of Th17 and Th2 that are able to induce IL‐17 and IL‐4 production." (PMID 29577333, 2018). "Both IL-4 and IL-13 receptors have been shown to be essential for fibrosis development in S. mansoni granuloma formation." (PMID 26962470, 2015).